LATS1 (large tumor suppressor kinase 1)
Description:
Negative regulator of YAP1 in the Hippo signaling pathway that plays a pivotal role in organ size control and tumor suppression by restricting proliferation and promoting apoptosis. The core of this pathway is composed of a kinase cascade wherein STK3/MST2 and STK4/MST1, in complex with its regulatory protein SAV1, phosphorylates and activates LATS1/2 in complex with its regulatory protein MOB1, which in turn phosphorylates and inactivates YAP1 oncoprotein and WWTR1/TAZ. Phosphorylation of YAP1 by LATS1 inhibits its translocation into the nucleus to regulate cellular genes important for cell proliferation, cell death, and cell migration. Acts as a tumor suppressor which plays a critical role in maintenance of ploidy through its actions in both mitotic progression and the G1 tetraploidy checkpoint. Negatively regulates G2/M transition by down-regulating CDK1 kinase activity. Affects cytokinesis by regulating actin polymerization through negative modulation of LIMK1. May also play a role in endocrine function. Plays a role in mammary gland epithelial cell differentiation, both through the Hippo signaling pathway and the intracellular estrogen receptor signaling pathway by promoting the degradation of ESR1. Acts as an activator of the NLRP3 inflammasome by mediating phosphorylation of 'Ser-265' of NLRP3 following NLRP3 palmitoylation, promoting NLRP3 activation by NEK7.
Synonyms: WARTS; wts
Tractability: Small molecule: a structure with a bound ligand is known; a high-quality ligand is known; it belongs to a druggable protein family. PROTAC: it is named in the literature on targeted protein degradation; ubiquitination databases record sites on it; its protein half-life has been measured; a small molecule that binds it is known.
Target class: Kinase; Enzyme; Protein Kinase; AGC protein kinase group; AGC protein kinase NDR family
Gene: Protein-coding gene on chromosome 6 (149,658,153 to 149,718,105, reverse strand). Ensembl gene ENSG00000131023.
Subcellular location: Cytoplasm, cytoskeleton, microtubule organizing center, centrosome; Cytoplasm, cytoskeleton, spindle; Midbody; Cytoplasm, cytoskeleton, microtubule organizing center, spindle pole body
Pathways (Reactome):
Signal Transduction: Signaling by Hippo
Gene Ontology:
Molecular function: ATP binding; magnesium ion binding; nuclear estrogen receptor binding; protein binding; protein kinase binding; protein serine kinase activity; protein serine/threonine kinase activity; protein kinase activity
Biological process: G2/M transition of mitotic cell cycle; hippo signaling; mammary gland epithelial cell differentiation; negative regulation of canonical Wnt signaling pathway; negative regulation of cyclin-dependent protein serine/threonine kinase activity; negative regulation of protein localization to nucleus; positive regulation of NLRP3 inflammasome complex assembly; protein phosphorylation; regulation of actin filament polymerization; regulation of intracellular estrogen receptor signaling pathway; regulation of protein-containing complex assembly; regulation of ubiquitin-dependent protein catabolic process; sister chromatid segregation; G1/S transition of mitotic cell cycle; hormone-mediated signaling pathway; positive regulation of apoptotic process; regulation of organ growth; regulation of transforming growth factor beta receptor signaling pathway; mitotic cell cycle phase transition; regulation of postsynaptic density assembly
Cellular component: cytoplasm; microtubule organizing center; midbody; spindle pole; cytosol; nucleus; centrosome; glutamatergic synapse; postsynapse; spindle
Genetic constraint (gnomAD): Loss-of-function variants: 21 observed, 94.83 expected, observed/expected ratio (o/e) 0.22, 90% interval 0.16 to 0.32. The upper end of that interval is the gene's LOEUF score, 0.32, which puts it in group 1 of 6, group 1 being the genes least tolerant of losing a copy. Missense variants: 972 observed, 1,361.8 expected, observed/expected ratio (o/e) 0.71, 90% interval 0.68 to 0.75. Synonymous variants: 450 observed, 457.8 expected, observed/expected ratio (o/e) 0.98, 90% interval 0.91 to 1.06.
Cancer hallmarks: escaping programmed cell death (suppresses); genome instability and mutations (suppresses); suppression of growth (promotes)
Homologues: Orthologues: chimpanzee LATS1 (99% identical), macaque LATS1 (99% identical), dog LATS1 (96% identical), pig LATS1 (95% identical), rabbit LATS1 (95% identical), rat Lats1 (94% identical), mouse Lats1 (93% identical), guinea pig LATS1 (81% identical), tropical clawed frog lats1 (74% identical), zebrafish lats1 (63% identical), Drosophila melanogaster wts (42% identical), Caenorhabditis elegans wts-1 (30% identical), and 1 more. Paralogues in human: LATS2 (51% identical), MAST2 (22% identical), MAST4 (21% identical), MAST1 (20% identical), MAST3 (19% identical), DMPK (14% identical), MASTL (13% identical), SGK1 (12% identical), SGK3 (12% identical), STK32C (11% identical), SGK2 (11% identical), STK32B (9% identical), and 1 more.
Diseases named in the same sentence as LATS1 in open-access papers:
LATS1 is named in the same sentence as 163 diseases in open-access papers, as found by Europe PMC text mining. Sharing a sentence is not in itself a finding about the gene and the disease. The quoted sentences say what the papers report.
breast cancer (91 papers, 2009 to 2025). A primary or metastatic malignant neoplasm involving the breast. "Inhibitors of YAP/TAZ-TEAD activity block mammary carcinomas and associated stromal changes resulting from LATS1/2-inactivation." (PMID 39953252, 2025). "Here, altered gene expression and chromatin structure linked to LATS1 kinase signaling is found in 3D spheroids grown from breast cancer cells." (PMID 38565950, 2024). "Our analysis showed that loss of one or more alleles of LATS1 or LATS2 is widespread amongst human breast cancers, with the most notable loss in the basal subtype." (PMID 36443313, 2022). "Gene expression analyses of LATS1/2-deleted mammary epithelial cells notably revealed a transcriptional program that associates with human basal-like breast cancers." (PMID 36443313, 2022). "On the other hand, LATS1 expression was significantly elevated in breast cancers harboring an inactivating mutation in the NCOR1 gene, relative to those harboring wild-type NCOR1." (PMID 36443319, 2022). "To assess the impact of LATS1/2 loss, we evaluated LATS1/2 copy-number alterations and LATS1/2-regulated gene signatures across the different breast cancer subtypes." (PMID 36443313, 2022). "These analyses together point to a transcriptional association between Sox9 levels and genes upregulated with LATS1/2 deletion in human basal-like breast cancers." (PMID 36443313, 2022). "Consistent with the aggressive traits associated with basal breast cancers, loss of LATS1/2 resulted in the development of metastatic tumors." (PMID 36443313, 2022). "Here the authors report that LATS1 limits the progression of luminal breast cancer by associating with NCOR1 nuclear corepressor to repress ERα-downregulated genes in luminal cells." (PMID 36443319, 2022). "In breast cancer, colorectal cancer, gastric cancer, and lung cancer, LN metastasis is associated with decreased LATS1/2 expression." (PMID 36552980, 2022). "Depletion or downregulation of LATS1, as occurs in many breast cancer tumors, leads to epigenetic promiscuity and predisposes breast cancer cells to express basal-like genes." (PMID 36443319, 2022). "Breast cancer cell plasticity caused by LATS1 dysfunction contributes to increased tumor aggressiveness and, presumably, therapy resistance." (PMID 36443319, 2022). "The reduced interaction between the super enhancer and ESR1 promoter locus in LATS1/2 deficient cells was further validated by multiplexed in-situ UMI-4C-seq in another ER+ breast cancer line T47D." (PMID 35217640, 2022). "Our study demonstrates in vivo roles for the LATS1/2 kinases in mammary epithelial homeostasis and luminal-basal fate control and implicates signaling networks induced upon the loss of LATS1/2 activity in the development of basal-like breast cancer." (PMID 36443313, 2022). "In summary, our results demonstrate that conditional loss of LATS1/2 in the mature mouse luminal mammary epithelium results in the development of mammary carcinomas with basal-like traits." (PMID 36443313, 2022). "Hypermethylation of the LATS1 and LATS2 promoters is observed in 50% of breast cancers, whereas genomic loss of LATS1, LATS2, and NF2 also occurs in TNBC." (PMID 29562176, 2018). "The hypermethylation of the promoter region of LATS1 gene (50% of breast tumors) is associated with an aggressive breast cancer phenotype and poor survival." (PMID 27759563, 2016). "Low expression of LATS1 is associated with poor prognosis and contributes to the biologically aggressive phenotype in breast cancer." (PMID 25712415, 2015). "For instance, a genome-wide association study (GWAS) of 19,091 cases with breast cancer and 20,606 controls has identified the SNP rs9485372 in chromosome 6q25.1 near the LATS1 gene, and associated it with risk to breast cancer." (PMID 25628642, 2014).
breast cancer (continued). "Overexpressed LATS1 not only causes G2-M arrest through the inhibition of CDC2 kinase activity in breast cancer cell line in vitro, but also significantly inhibited the tumorigenicity in vivo by inducing apoptosis." (PMID 22909338, 2012). "The human LATS1 gene has been mapped to chromosome 6q24-25 where loss of heterozygosity has been observed in ovarian, cervical, and breast cancers." (PMID 22909338, 2012). "Loss-of-heterozygosity (LOH) of the LATS1 chromosomal locus at 6q24-25.1 has been reported in a fraction of human breast cancers and salivary duct carcinomas, but inactivating point mutations have not been found." (PMID 19656388, 2009). "Furthermore, we found that the increased sensitivity of breast cancer cells was closely associated with the LATS1-mediated degradation of ER-α." (PMID 37924380, 2024). "Thus, LATS1 can favor luminal cell identity in mouse and human breast cancer cells, in association with the downmodulation of H3K27ac." (PMID 36443319, 2022). "We found that LATS1/2 loss in the mature luminal mammary epithelium in vivo resulted in striking gene expression changes that align with transcriptional signatures observed in human basal-like breast cancers." (PMID 36443313, 2022). "Taken together, these data suggest that MDA-MB-231 breast cancer cells may have positively selected for the pPA-truncated product of LATS1 as a potentially oncogenic protein variant." (PMID 29362392, 2018). "Furthermore, recent investigations demonstrated that hypermethylation of LATS1 gene promoter which caused downregulated expression of LATS1 is frequently observed in a few human tumors, such as breast cancer and astrocytoma." (PMID 22909338, 2012). "In this study we used a genetic mouse model of basal-like breast cancer driven by epithelial-specific inactivation of the Hippo pathway-regulating LATS1 and LATS2 kinases to elucidate epithelial-stromal interactions." (PMID 39953252, 2025). "Here we show that Hippo dysregulation through Lats1/2 deletion in the luminal mammary epithelium is sufficient to drive dramatic stromal remodeling resembling phenotypes observed in human breast cancers." (PMID 39953252, 2025). "In this study we demonstrated that basal-like mammary carcinomas driven by Lats1/2 inactivation exhibit changes to epithelial, fibroblast, and immune cell populations." (PMID 39953252, 2025). "As well, inactivation of LATS1/2 was found to drive luminal-basal plasticity and initiate basal-like mammary carcinomas." (PMID 40157909, 2025). "To confirm expression of PDGF and TGF-β ligands in Lats1/2-null mammary carcinomas, we performed RNAscope in situ hybridization." (PMID 39953252, 2025). "We show that basal-like mammary carcinomas initiated by deletion of Lats1/2 in luminal mammary epithelial cells is sufficient to promote stromal cell remodeling and ECM accumulation resembling the phenotypes observed in human triple-negative tumors." (PMID 39953252, 2025). "Together, this data demonstrates that CAFs present in the stroma of mammary carcinomas driven by Lats1/2 inactivation share similarities to CAFs in human TNBC, and that stromal CAF alterations develop during early initiation of basal-like carcinomas." (PMID 39953252, 2025). "Most of the stromal cells that accumulated within the Lats1/2-null mammary carcinomas were enriched in the expression of ECM-related genes, including those encoding Collagens, Laminins, Thrombospondin, Fibronectin, and Tenascin." (PMID 39953252, 2025). "For example, CRABP2 inhibits the invasion and metastasis of ER + breast cancer and facilitates the metastasis of ER- breast cancer by regulating the stability of Lats1." (PMID 38807101, 2024). "We found that breast cancer 3D spheroids showed high expression of key genes involved in tumor growth, as well as LATS1-dependent nuclear receptor binding features shared with PDXs but absent in 2D cells." (PMID 38565950, 2024).
breast cancer (continued). "METTL3 was identified as the m6A writer, with YTHDF2 as the reader protein of LATS1 mRNA, which plays a positive role in promoting both tumorigenesis and glycolysis in breast cancer." (PMID 36609396, 2023). "We conducted RNA pull-down assays, RIP-qPCR, MeRIP-qPCR, and RNA stability analysis to identify the relationship between m6A proteins and LATS1 in m6A regulation in breast cancer cells." (PMID 36609396, 2023). "LATS1 protein is reported to be downregulated in a variety of human tumors, including cervical cancer, lung cancer, breast cancer, colorectal cancer and ovarian cancer." (PMID 36803368, 2023). "Combined analysis of the multiple sequencing results revealed that METTL3 participates in the inhibition of LATS1 and affects tumorigenesis and metabolism in breast cancer cells." (PMID 36609396, 2023). "Knockout of the protein expression of METTL3 or YTHDF2 increased the expression of LATS1 mRNA and suppressed breast cancer tumorigenesis by activating YAP/TAZ in the Hippo pathway." (PMID 36609396, 2023). "We demonstrated that m6A regulation plays an important role in proliferation and glycolytic metabolism in breast cancer through the Hippo pathway factor, LATS1." (PMID 36609396, 2023). "To determine the impact of YTHDF2 in breast cancer cells and understand its role in the m6A methylation of LATS1 mRNA in tumorigenesis and glycolysis, we altered the expression of YTHDF2 in breast cancer cells." (PMID 36609396, 2023). "In ER+ breast cancer cell lines, LATS1/2, upstream inhibitors of YAP1, are required to maintain ER+ cancer cell growth while little effect was observed in ER− cancer cells." (PMID 37894401, 2023). "Since a high m6A modification level of LATS1 mRNA was found by MeRIP-seq, we aimed to determine which m6A readers directly recognize m6A modification sites and regulate the expression of LATS1 in breast cancer cells." (PMID 36609396, 2023). "Previous studies have shown that WWP1 promotes the proliferation of breast cancer cells by binding and ubiquitinating the LATS1 protein." (PMID 36803368, 2023). "DPPA, a phosphatidic acid, was previously identified as a potent accelerator of YAP/TAZ signaling by LATS1/2 kinase inhibition in breast cancer cells." (PMID 36674487, 2023). "A study reported that METTL3 regulates glycolysis by regulating m6A methylation of the key molecule of the Hippo pathway, LATS1, in breast cancer." (PMID 37684641, 2023). "We found that m6A methylation of LATS1 downregulated LATS1 expression in breast cancer cells and activated YAP/TAZ by inhibiting its phosphorylation." (PMID 36609396, 2023). "Such m6A sites of LATS1 mRNA can be recognized by YTHDF2, which promotes the degradation of LATS1 mRNA and eventually tumorigenesis and glycolysis in breast cancer cells." (PMID 36609396, 2023). "Intriguingly, when the expression of large tumor suppressor kinases 1 and 2 (LATS1 and 2) is reduced, the sensitivity to fulvestrant of breast cancer cells is decreased." (PMID 35498431, 2022). "A recent report demonstrates that LATS1/2 promotes breast cancer cell growth through inhibition of YAP/TAZ." (PMID 35967587, 2022). "To assess the phenotypic impact of LATS1 in human breast cancer cells, we subjected MDA-MB-468 cells to FACS analysis, employing EpCAM as a luminal marker." (PMID 36443319, 2022). "In agreement with our observations, another study deleted LATS1 in the PyMT luminal B breast cancer mouse model and showed that the developing tumors adopt basal-like traits, including loss of ER expression and acquisition of K1451." (PMID 36443313, 2022). "Expression of such genes was suppressed also upon overexpression of LATS1 in MDA-MB-468 human basal-like breast cancer cells (right)." (PMID 36443319, 2022). "High levels of LATS1/2 are detected in patients with breast cancer ERα– and short relapse-free survival." (PMID 35498431, 2022).